COMT (catechol-O-methyltransferase)
Diseases named in the same sentence as COMT in open-access papers (continued):
Sharing a sentence is not in itself a finding about the gene and the disease.
schizophrenia (continued). "For example, the expression of the susceptibility gene COMT in schizophrenia is related to the size and function of DLPFC." (PMID 34879837, 2021). "The study found a significant therapeutic response in schizophrenia patients with the COMT rs4680 A (adenine) allele and rs4680-rs4818 CA (cytosine-adenine) haplotype, who were treated with olanzapine, an atypical antipsychotic drug." (PMID 34725583, 2021). "A longitudinal study done in 2020 looked at the association between two genotypes of COMT - rs4680 and rs4818 and response to treatment with antipsychotic drugs in 521 Caucasian schizophrenia patients." (PMID 34725583, 2021). "In patients with schizophrenia, the COMT rs4680 genotype was associated with antipsychotic-induced dopamine hypersensitivity and resistance to antipsychotics." (PMID 34287249, 2021). "The COMT Val allele has been associated with positive symptoms in schizophrenia, while Met homozygosity is associated with positive symptoms in bipolar disorder also supporting a differential role in the clinical expression of the disorder." (PMID 32950905, 2020). "COMT promoter methylation studies in 115 postmortem brain samples from the frontal lobe of schizophrenia patients, revealed that the promoter of the gene encoding the membrane-bound isoform is frequently hypomethylated." (PMID 32764320, 2020). "Variation in the Catechol-O-methyltransferase gene was differentially associated with P3b in schizophrenia and bipolar groups." (PMID 32950905, 2020). "Associations between schizophrenia and SNPs in COMT and DRD3 genes are still controversial, there are studies both confirming and refuting these relationships." (PMID 31798476, 2019). "A specific example of genetic involvement in the cannabis/schizophrenia association can be seen in the COMT gene." (PMID 31661851, 2019). "Individuals with 22q11.2DS present several phenotypic traits such as risk of schizophrenia, intellectual disability and math learning difficulties in the presence of hemizygosis at the COMT Val158Met locus." (PMID 31156495, 2019). "Distribution of DRD3, COMT, and 5HT2A polymorphisms in youth-onset schizophrenia and control groups." (PMID 31798476, 2019). "Haplotype frequencies of COMT rs4680 and rs4818 polymorphisms in male patients with schizophrenia subdivided according to the TRS." (PMID 30018555, 2018). "In this study, the aim was to conduct a meta‐analysis to achieve a pooled effect size of the association between COMT gene rs165599 SNP and schizophrenia." (PMID 30165727, 2018). "Variants of the COMT gene have been extensively studied as risk factors for schizophrenia; however, their association with TRS has been poorly investigated." (PMID 30018555, 2018). "For instance, a recent study has shown possible epigenetic modulation of the expression of the COMT Val158Met polymorphism and subsequent effects on the relationship between traumatic life events and cognition in schizophrenia." (PMID 28822116, 2018). "Haplotype frequencies of COMT rs4680 and rs4818 polymorphisms in female patients with schizophrenia subdivided according to the TRS." (PMID 30018555, 2018). "Catechol-O-methyltransferase (COMT), an enzyme responsible for degrading catecholamine, including DA and NE, has been implicated in schizophrenia and many mental disorders, and it has also been associated with creativity." (PMID 30429805, 2018). "There are many studies with different results that examine the association between Catechol‐O‐MethylTransferase (COMT) gene single‐nucleotide polymorphisms (SNPs) and schizophrenia." (PMID 30165727, 2018). "Our results confirmed gender-related differences in the genotypic and haplotypic association of the COMT rs4680 and rs4818 and treatment resistance in patients with schizophrenia." (PMID 30018555, 2018). "COMT gene variability has been associated with cognitive performance in schizophrenia and with CR response, although results have been equivocal." (PMID 30687100, 2018).
schizophrenia (continued). "In our study, the impact of COMT rs4680 polymorphism on the clinical symptomatology of schizophrenia has also been exposed." (PMID 29429137, 2018). "This region is highly implicated in schizophrenia both as the location of several schizophrenia candidate genes, including catechol-O-methyltransferase (COMT), and due to its involvement in DiGeorge syndrome." (PMID 29657307, 2018). "The present study aimed to extensively evaluate the contribution of DAOA and COMT genes in susceptibility to schizophrenia and bipolar I disorder." (PMID 30719257, 2018). "The association between COMT rs4818 and treatment response to risperidone was also reported in 288 Shanghai patients with schizophrenia, but opposed to our and their previous results, the G/C allele frequency was similar between good and poor responders." (PMID 30018555, 2018). "The catechol-O-methyltransferase (COMT) gene with its val158met polymorphism have been extensively studied in psychiatric genetics (mainly in relation to schizophrenia)." (PMID 29019461, 2017). "Genes associated with schizophrenia and antipsychotic drug response include the catechol-O-methyl transferase (COMT) gene, coding for an enzyme involved in the catabolism and regulation of DA levels in the PFC." (PMID 28358316, 2017). "Mutations in the LRTOMT gene, which encodes a protein with homology to the catecholamine methyltransferase COMT that is linked to schizophrenia, cause deafness." (PMID 28504928, 2017). "Other reports also demonstrated the association of additional COMT polymorphisms and haplotypes with schizophrenia, as well as the synergistic effects of COMT gene with genes involved in other neurotransmitter systems." (PMID 28358316, 2017). "Various studies linked schizophrenia with a region on chromosome 22q11.2, where the COMT gene has been located." (PMID 28358316, 2017). "Our results also agree with previous preliminary findings on the link between the COMT Val158Met polymorphism and pursuit eye movements that have been reported for healthy control subjects in a clinical study in schizophrenia patients." (PMID 28101524, 2016). "In particular, studies in children, and in clinical syndromes such as schizophrenia, have consistently shown that those homozygous for the Val allele of COMT gene perform significantly more poorly on tasks of executive function than Met-allele carriers." (PMID 26974654, 2016). "Although COMT has been associated with psychotic and mood disorders including schizophrenia and bipolar disorder, results have been inconsistent." (PMID 27622935, 2016). "Our study shows that the impact of COMT polymorphism differs according to each domain like in previous studies of Parkinson’s disease and schizophrenia." (PMID 27657697, 2016). "While the COMT gene is located in a region associated with high schizophrenia risk (22q11), associations between the gene itself and schizophrenia have been inconsistent." (PMID 25762938, 2015). "Genetic variations in dopaminergic genes such as catechol-O-methyltransferase (COMT), which breaks down dopamine after release, have also been linked to schizophrenia." (PMID 25814948, 2015). "Allelic expression has been analyzed based on mRNA expression and revealed that the catechol-O-methyltransferase gene (COMT) is a susceptibility gene for schizophrenia that is downregulated in the autopsy brain tissues of patients." (PMID 25951941, 2015). "Catechol-O-methyltransferase (COMT) is a candidate susceptibility gene for schizophrenia that is involved in the regulation of dopamine in the prefrontal cortex." (PMID 25722988, 2015). "Other investigators, who also had small sample studies, have reported associations between COMT and other psychiatric conditions, such as schizophrenia, bipolar disorder; alcoholism, substance use disorders, depression, and anorexia nervosa." (PMID 25793616, 2015).
schizophrenia (continued). "Nevertheless, COMT – particularly the Val158Met allele – is associated with a number of human endophenotypes, which are important in schizophrenia and depression, including PFC-mediated cognition, variations in brain structure, and anxiety traits." (PMID 25762938, 2015). "For example, cannabis use and having the catechol-o-methyl transferase (COMT) valine allele are separately implicated as schizophrenia risk factors and the functional polymorphism in the COMT gene has been found to alter the effects of cannabis." (PMID 24671152, 2014). "List of major studies documenting an interaction between COMT polymorphic variants and sex in schizophrenia and related symptoms." (PMID 24639636, 2014). "For example, hypomethylation of the COMT gene has been associated with both bipolar disorder and schizophrenia." (PMID 25202283, 2014). "As a result of its ubiquity, COMT has been implicated in a wide range of human conditions, including cancer, pain sensitivity, schizophrenia, affective, addictive, impulse control disorders, and Parkinson’s disease." (PMID 24460628, 2014). "COMT encodes for a cytosolic enzyme that acts to degrade neuroactive monoamines such as dopamine and it has been considered a possible candidate gene for schizophrenia and other psychiatric disorders." (PMID 25084529, 2014). "The functional polymorphism Val158Met in the catechol-O-methyltransferase (COMT) gene has been associated with differences in prefrontal cognitive functions in patients with schizophrenia and healthy individuals." (PMID 24282499, 2013). "Until recently, Catechol-O-methyltransferase (COMT) was the only candidate for a possible interaction between a genetic predisposition for schizophrenia and heavy cannabis abuse [but see also]." (PMID 23966917, 2013). "Hypomethylation of the COMT gene, which leads to an increase in the enzyme that breaks down DA, has been associated with schizophrenia and bipolar disorder." (PMID 24391541, 2013). "An association that has been suggested to be relevant is the schizophrenia risk gene, COMT, that also been implicated in BOLD signal activation during working memory tasks." (PMID 25379242, 2013). "The gene coding for catecol-o-methyltransferase (COMT), participant in the metabolism of catecholamines, has long been implicated as a candidate gene for schizophrenia." (PMID 23184041, 2013). "In general, the COMT Val108/158Met polymorphism appears to have little if any direct association with cognitive functioning, with mixed results in patients with schizophrenia and bipolar disorder, as well as in healthy controls." (PMID 23421957, 2013). "These investigations are in keeping with a substantial gene association literature implicating polymorphism in COMT to schizophrenia susceptibility." (PMID 23805071, 2013). "More recently, methylation of CpG sites in the promoter region of COMT has been linked to psychiatric diagnoses such as schizophrenia, bipolar disorder, and nicotine dependence as well as prefrontal cognition and activity." (PMID 23596403, 2013). "COMT helps in the metabolism of DA, adrenalin, and norepinephrine and has been implicated in the etiology of substance abuse, schizophrenia, and novelty seeking, as well as ADHD." (PMID 24163823, 2013). "In this study, a population of Mexican schizophrenic patients was investigated to explore the association between COMT Val108/158Met and schizophrenia." (PMID 23184041, 2013). "For example, it has been suggested that the catechol-O-methyltransferase Val158Met polymorphism has an opposite effect on verbal fluency in healthy controls compared with patients with schizophrenia." (PMID 24168225, 2013). "Subsequent studies of violence and the COMT polymorphism in schizophrenia were conducted to replicate and expand these findings." (PMID 22905266, 2012). "Substance abuse elevates the risk of violence in schizophrenia, and it is possible that this effect is partially moderated by the COMT polymorphism." (PMID 22905266, 2012).
schizophrenia (continued). "Specifically, a functional single nucleotide polymorphism (Ala72Ser) in the COMT gene has been shown to differentiate schizophrenia patients who commit homicide." (PMID 22905266, 2012). "It is therefore of interest that the Met allele in the COMT genotype was associated with the history of violent suicide attempts in schizophrenia patients and with suicide attempts in alcoholics." (PMID 22905266, 2012). "We conclude that male schizophrenia patients who carry the low activity Met allele in the COMT gene are at a modestly elevated risk of violence." (PMID 22905266, 2012). "Recent studies evaluating the role of catechol-O-methyltransferase enzyme (COMT) polymorphisms in the pathogenesis of schizophrenia have resulted in ambiguous findings." (PMID 23762769, 2012). "Information was collected on 2,370 individuals with schizophrenia from 15 retrospective investigations of the association between the Val158Met polymorphism of the COMT gene and physical violence against others." (PMID 22905266, 2012). "Our principal finding is that the presence of one or more Met alleles in the COMT genotype elevates interpersonal violence risk in male schizophrenia patients." (PMID 22905266, 2012). "Several genes located in the 22q11 region have been linked to schizophrenia, including COMT, ProDH, Ufd1L, PCQAP, and, recently, GNB1L." (PMID 22457764, 2012). "Among these are the genes which have been previously associated with schizophrenia, COMT, Ufd1L, PCQAP, and GNB1L." (PMID 22457764, 2012). "The current study examined the association of schizophrenia with three COMT polymorphisms, namely, rs737865, rs4680, and rs165599 in a Greek population." (PMID 23762769, 2012). "Recently we identified two SNPs in COMT (rs4680 and rs165774) that are associated with schizophrenia in an Australian cohort." (PMID 22208661, 2011). "Previously we confirmed that rs4680 is associated with schizophrenia in an Australian population but we have identified stronger association with schizophrenia with a novel COMT SNP, rs165774." (PMID 22208661, 2011). "This study identified a polymorphism in COMT that possibly plays a role in psychiatric liability for schizophrenia and alcohol dependence." (PMID 22208661, 2011). "Two SNPs in COMT previously identified as being associated with schizophrenia were examined for their association with alcohol, nicotine and opiate dependence." (PMID 22208661, 2011). "The only other non-synonymous polymorphism in COMT that has been found to be associated with schizophrenia is rs6267." (PMID 22208661, 2011). "The COMT gene is located on chromosome 22q11 and association studies have identified a number of polymorphisms that are associated with schizophrenia." (PMID 22208661, 2011). "Along with schizophrenia, studies have also identified COMT associations with a range of psychiatric conditions." (PMID 22208661, 2011). "It is possible that the rs165774 SNP, in combination with rs4680, results in a common molecular variant of COMT that contributes to schizophrenia and alcohol dependence susceptibility." (PMID 22208661, 2011). "They observed highly significant association of seven COMT marker haplotypes with schizophrenia (CLUMP T4 P-value = 0.0001)." (PMID 21836667, 2010). "A number of studies have evaluated the association between the Val108/158Met polymorphism (rs4680) in the COMT gene, encoding catechol-O-methyltransferase, which catalyzes the metabolism of dopamine, and schizophrenia risk." (PMID 21217836, 2010). "The 3'-flanking region of SNP rs165599 exhibited significant allelic differences in expression in the human brain, and the A allele in schizophrenia patients is associated with higher expression of the COMT gene." (PMID 21217836, 2010). "We have previously reported that NRG1-stimulated migration of B lymphoblasts is PI3K-AKT1dependent and impaired in patients with schizophrenia and significantly linked to the catechol-o-methyltransferase (COMT) Val108/158Met functional polymorphism." (PMID 20520724, 2010).
schizophrenia (continued). "Polymorphisms in COMT are often associated with CNS diseases such as schizophrenia, anorexia nervosa, bipolar disorder, anxiety, and substance use disorders." (PMID 20808911, 2010). "This minor SNP, producing an alanine to serine substitution at codon 72, has been associated with aggressive behavior and schizophrenia risk as well as with COMT activity in red blood cells collected from study participants." (PMID 19365560, 2009). "A previous report demonstrated that the minor allele of rs2097603 located in the MB-COMT promoter region associated with schizophrenia was found to produce a 1.5-fold reduction in lymphocyte COMT activity independent of the val158met allele." (PMID 19365560, 2009). "COMT polymorphisms also appear to disturb neurocognitive functions and by doing so increase susceptibility to schizophrenia." (PMID 19445674, 2009). "For example, the catechol-o-methyltransferase (Comt) gene is expressed in the brain and associated with the etiology of schizophrenia and depression." (PMID 19015723, 2008). "The presence of the schizophrenia risk-associated COMT val allele showed a strong trend towards predicting smaller NRG1α-induced MRVA in the entire sample with similar effects in both groups (unpaired t-test, p = 0.0632)." (PMID 18159252, 2007). "Lastly, a single nucleotide polymorphism within COMT, a gene implicated in susceptibility both to schizophrenia and to metastatic cancer, demonstrates a strong trend towards predicting the MRVA of a given cell line, even in normal subjects." (PMID 18159252, 2007). "Previous research has suggested that activity and expression of COMT is altered in schizophrenia, and is mediated by one or more polymorphisms within the gene, including the functional Val158Met polymorphism." (PMID 16483362, 2006). "In this study we have examined expression of the Catechol-O-Methyltransferase (COMT) gene, primarily associated with schizophrenia, but also linked to other forms of psychopathology and variation in normal prefrontal cognitive functioning." (PMID 16483362, 2006). "The COMT gene maps to chromosome 22q11.2, a region implicated in schizophrenia linkage studies, and in velocardiofacial syndrome (VCFS), which is characterized by psychosis and cognitive deficits." (PMID 17173666, 2006). "Overall, the available data suggest there is a haplotype spanning COMT associated with a slightly elevated risk to schizophrenia, which confers a decrease in expression in COMT mRNA." (PMID 16483362, 2006). "The COMT gene is implicated in the pathophysiology of schizophrenia by its effect on prefrontal dopamine." (PMID 17173666, 2006). "The COMT gene is located on chromosome 22q11, a region strongly implicated in the aetiology of several psychiatric disorders, in particular schizophrenia." (PMID 16483362, 2006). "We have previously demonstrated association between COMT 158 Val allele and schizophrenia in a biracial cohort of patients from the Baltimore Metropolitan area." (PMID 17173666, 2006). "Given that dopamine dysregulation is a well-established hallmark of schizophrenia, miR-34a-mediated alterations in COMT expression could have profound implications for disease progression and symptom severity." (PMID 40779062, 2026). "Among the most studied genetic variants, the COMT Val158Met polymorphism was frequently associated with prefrontal cortex and hippocampal function, particularly in schizophrenia and mood disorders, where it influenced cognitive control and emotional regulation." (PMID 40360788, 2025). "The COMT gene is localized in chromosome 22q11, one of the principal loci linked to schizophrenia." (PMID 40243512, 2025). "IL-10 and COMT gene polymorphisms were found to interact with cognitive function in patients with schizophrenia, suggesting that COMT may influence immune responses through interaction with anti-inflammatory cytokines." (PMID 40299330, 2025).